CDK2 (cyclin dependent kinase 2)
Diseases named in the same sentence as CDK2 in open-access papers (continued):
Sharing a sentence is not in itself a finding about the gene and the disease.
cancer (continued). "To determine the potential contribution of inhibiting CDK3 and CDK5, as compared to CDK2 and CDK9, we analyzed data publicly available from genome-wide CRISPR-Cas9 screens in >700 cancer cell lines (from the Cancer Dependency Map project)." (PMID 32645016, 2020). "In this case, knockdown of CDK20 leads to G1 phase cell cycle arrest and decreased CDK2 phosphorylation, suppressing the growth of glioma cells in vivo, implicating CDK20 as an oncogene for this type of cancer." (PMID 33198081, 2020). "Several leads were identified and, of these, 19 demonstrated the best CDK2 inhibition (IC50 = 6.8 μM) and low-micromolar potency against two cancer cell lines." (PMID 33479617, 2020). "We show that fadraciclib demonstrates improved kinase inhibitory potency in vitro against its primary CDK targets–CDK2 and CDK9 –as well as anti-cancer activity in in vitro and in vivo models." (PMID 32645016, 2020). "We previously reported a lead compound from this series, CCT068127, with reduced metabolism, enhanced selectivity towards CDK2 and CDK9 and superior therapeutic activity against human cancer cells." (PMID 32645016, 2020). "Mechanistically, TTK exerted a significant enhancement in cancer growth by neurotensin (NTS) upregulation, and subsequently increased the expression of cyclin A and cdk2, which was resulting in the increase of DNA synthesis." (PMID 32121246, 2020). "Hence, activation of CDK2, independent of CDK4/6 activity, may limit the potency of CDK4/6is in cancers, and identification of signalling required for CDK2 activation may yield information that predicts CDK4/6 inhibitor response, or be exploited to extend their efficacy in cancer therapy." (PMID 31296956, 2019). "Given the relevance of this pathway in cancer biology, further studies are warranted to clarify the molecular mechanisms linking CK2 with the CDK2/cyclin E pathway." (PMID 31641101, 2019). "In the cell cycle pathway, GSK3B, CDK2, and CDK1 are reduced by cisplatin in each cell line, and in cancer pathways, cisplatin reduces phosphorylation of GSK3B, AKT1, PDGFRa/b, PLCG1/2, and CDK2." (PMID 31929796, 2019). "CDK7 is considered as an attractive target for treating human cancer, as it controls the activity of key enzymes involved in cell cycle progression, including other cyclin-dependent kinases such as CDK1, CDK2, CDK4, and CDK6." (PMID 31076643, 2019). "Fortunately, our work found that CDK1 and CDK2 interact with multiple ingredients for CKI, including adenine, and macrozamin, and CKI has been shown to have therapeutic effects on cancer through inhibiting CDK2 activity." (PMID 31275410, 2019). "KLF6 is frequently inactivated in HCC and, when overexpressed in carcinoma-derived cells, interacts with cyclin D to disrupt cyclin/CDK complexes, to redistribute p21 to CDK2, which promotes G1 cell cycle arrest." (PMID 30774659, 2019). "Our data suggest that dual inhibition of CDK2 and BET bromodomains can be a novel treatment approach for suppressing MYC-driven cancer." (PMID 29511348, 2018). "In particular, the four overlap non-cancer genes (CDK1, CDK2, PLK1 and WEE1), which were validated by the three data resources, were all known anticancer drug targets and clinical trial targets." (PMID 29855504, 2018). "Our results illustrated that gene networks of cell cycle progression or cell proliferation (including: CDK2 and SMC4) are affected in both SOX2OT knock downed cancer cells." (PMID 30202240, 2018). "We observe that a few gene pairs have substantial evidence across all cancer types (e.g., CDK4 and CDK2 pair)." (PMID 30514202, 2018). "What possibilities are there to target the MYC/CDK2/SKP2/p27 axis in cancer, i.e., reducing the activity of MYC, CDK2 or SKP2, or boosting nuclear p27 expression?" (PMID 28665315, 2017).
cancer (continued). "These include cancer hallmarks of various types: oncogenes (BCL2, BRAF), caspases (CASP6/7), transcription factors (E2F3), cell cycle genes (CDC42, CDK2, CDKN2A), cancer related kinases (JAK2/3, MAPK4/6/14) and DNA repair genes (BRCA1, PARP1 and RAD50)." (PMID 28059167, 2017). "The other distinct class includes CDK inhibitors that are more selective for CDK1 and CDK2 as well as the transcriptional CDKs (CDK5, CDK7, and CDK9), and these drugs are being more widely studied in cancers including triple-negative breast cancer." (PMID 28107181, 2017). "While nuclear p27 acts as a break on the cell cycle by inhibiting CDK2 and MYC as discussed here, cytoplasmic p27 promotes cancer cell migration and invasion." (PMID 28665315, 2017). "CDK2, which can phosphorylates CIZ1 on T174, T222 and T323, is rarely found to be genetically or epigenetically altered in cancers." (PMID 26861296, 2016). "The critical well-known function of P21 is to block cell proliferation in normal and cancer cells by inhibiting the activity of kinases important for G1/S transition such as CyclinD/CDK4, CyclinD/CDK6 and CyclinE/CDK2." (PMID 26384350, 2015). "Dinaciclib, a novel small molecule inhibitor of CDK1, CDK2, CDK5 and CDK9, is assessed in clinical trials for the treatment of several types of cancers." (PMID 25962959, 2015). "In this study, we demonstrate that miR-188 exerts anti-cancer potential via downregulating multiple G1/S related genes, including CCND1, CCND3, CCNE1, CCNA2, CDK2 and CDK4." (PMID 25304455, 2014). "As a major event downstream of MYC activation, CDK2 activation can also suppress MYC-induced senescence, which raised the possibility of CDK2 as a potential therapeutic target for MYC-dependent cancers." (PMID 24444383, 2014). "The recently identified CDK9-targeted kinases, CDK7, CDK2, and phosphatases, PP1, and PPM1A will likely emerge as novel targets for anti-HIV-1 and cancer therapeutics." (PMID 24524087, 2014). "Western blotting revealed that CDK1, CDK2, CDK4 and CDK6 proteins were expressed at much higher levels in the carcinoma tissues than the matched normal tissues." (PMID 24765199, 2014). "CDK2 siRNA silencing and inhibition of CDK2 kinase activity using a CDK1, CDK2 and CDK9 inhibitor (AZD5438) resulted in significantly higher reduction in survival of cancer cells harbouring CCNE1 gene amplification." (PMID 22433433, 2012). "The first network suggests significant involvement of p30-interacting proteins with DNA recombination, repair, cell cycle and cancer with pathways clustering around ATM, cyclin E, cyclin A and CDK2." (PMID 22876852, 2012). "The hubs also include RB1, BCL2, AKT1, CDK2, CASP8 which are involved in mechanisms of apoptosis, to which cells are known to acquire resistance in all types of cancers." (PMID 23166660, 2012). "Of the proliferative factors analysed (PCNA, cyclin A, cyclin D, the cyclin-dependent kinases cdk2 and cdk4, cell cycle phases) only PCNA and cyclin A (CCNA) exhibited a relationship to sensitivity/resistance and were down-regulated in resistant carcinomas." (PMID 12177790, 2002). "For example, luteolin prevents cancer via modulation of numerous pathways—inactivates proteins, such as procaspase-9, CDC2, and cyclin B or upregulates caspase-9 and caspase-3, cytochrome C, cyclin A, CDK2, and APAF-1." (PMID 41304998, 2025). "This approach unveiled cancer cell-selective hits such as BUB1, CDK2, and VPS37A." (PMID 40180891, 2025). "Conversely, knockout of CDK2 can inhibit malignant proliferation and aerobic glycolysis of cancer cells by increasing SIRT5 expression, revealing a novel role for SIRT5 as a tumor suppressor regulated by upstream genes in cancer." (PMID 39944690, 2025). "If CDK2 inhibited the local immune response by virtue of its function as a kinase protein, reconstitution of Cdk2-/- cancer cells with WT but not the kinase inactive T160A mutant Cdk2 should reverse the phenotype." (PMID 40557162, 2025).
cancer (continued). "Knockout cancer cell lines and murine models lacking CDK2 or CDK4/6 expression revealed that each of these kinases can independently drive cellular proliferation." (PMID 40282469, 2025). "Finally, we connected HGF, CDK2, FADD, and other proteins to the cancer pathways in the KEGG database." (PMID 40470116, 2025). "Our focus also extended to CDK2 and VPS37A genes, both of unknown biological significance in MPM, whose depletion by CRISPR should selectively affect cancer cells." (PMID 40180891, 2025). "In summary, this study comprehensively explored the distinct cell fates that occur in aneuploid cancer cells that respond to CDK2 antagonism yet are not eliminated but persist in vivo despite that ongoing inhibition." (PMID 40232858, 2025). "Accordingly, we found that the enhanced MTX anti-tumor responses of Cdk2-/- cancer cells over WT cells were abolish with WT Cdk2 but not Cdk2T160A reconstitution." (PMID 40557162, 2025). "Similarly, INX-315, a next-generation CDK2 inhibitor, induced cell cycle arrest and senescence in CCNE1-amplified cancer models with durable tumor control." (PMID 41331376, 2025). "In cancer models that are genetically independent of CDK2, pharmacological inhibitors suppress cell proliferation by inducing 4N cell cycle arrest and increasing the expressions of phospho-CDK1 (Y15) and cyclin B1." (PMID 39924553, 2025). "CDK2 belongs to the CDK family and can phosphorylate a large number of transcription factors, involved in the regulation of a variety of cancer signaling pathways, and promote cancer development." (PMID 38200019, 2024). "Inhibiting the expression of CDK-2 can promote the apoptosis of cancer cells without harming normal cells." (PMID 39057425, 2024). "RB1 is frequently mutated in a number of cancers (7% in total, according to TCGA database), including sarcoma, bladder, endometrial, ovarian, breast, prostate and non-small cell lung (NSCLC) cancers, and the Rb protein is inactivated by high CDK4/6 or CDK2 activity." (PMID 38279263, 2024). "CDK2, a member of the cyclin-dependent kinase (CDK) family, phosphorylates numerous transcription factors and participates in various cancer signaling pathways, thereby promoting cancer development." (PMID 39274982, 2024). "While our compounds are not cytotoxic in cyclin overexpressing cancer contexts, disruption of the CDK2/cyclin PPI remains a viable anticancer strategy." (PMID 37270540, 2023). "In addition to its effect on apoptosis and the cell cycle, compound 6b appeared to inhibit various kinases, such as CDK2, EGFR, HER2, and VEGFR2, which are overexpressed in cancer cells." (PMID 36678593, 2023). "Although the requirement of CDK2 activity in tumor initiation and maintenance is still not clear, several studies have demonstrated that the depletion of CDK2 inhibits cancer cell growth and disrupts cell cycle progression." (PMID 37958642, 2023). "Cyclin E1 deletion emerged as the leading candidate suppressing cell proliferation in Rb-knockout cancer cells, corroborating that CDK2 activation drives cell-cycle entry in the absence of CDK4/6 activity." (PMID 38030655, 2023). "The resulting antitumor activity may, in turn, be derived from the inhibition of important molecular targets involved in cancer pathogenesis, including ADORA1, CDK2, and TRIM24." (PMID 37894709, 2023). "It remains to be seen whether redundancies in the CDK2/CCNE1 pathway (CDK1 for CDK2, CCNE2 for CCNE1) observed in normal cells pose another challenge of targeting this pathway in cancers." (PMID 36572991, 2023). "Overactivation of CDK2 activity may limit the potency of CDK4/6 inhibitors, and individual cancer cells with high cyclin E1 levels may increase CDK2 activity thus bypassing CDK4/6 blockade." (PMID 37369022, 2023).
cancer (continued). "Taken together, these results suggested that β-carboline-3-carboxylic acid dimers could arrest the cell cycle by suppressing TK1, DBF4, CCNA2, CDK2, and PLK1, together with influencing some cancer-related pathways to inhibit MG-63." (PMID 36325324, 2022). "Thus, this study demonstrates the anti-cancer effect of erdafitinib against LADC for the first time based on in vitro and in vivo models, whose activity is achieved by targeting CDK2 and regulating downstream E2F1-CDK1 signaling." (PMID 36235266, 2022). "As depicted, the productions of CDK2 and SKP2 were positively regulated by LEMD1 in cancer cells." (PMID 35286235, 2022). "Studies have reported that CDK2 overexpression indicates poor prognosis in patients with HCC, and inhibition of CDK2 activity could reverse the malignant phenotype of cancer cells." (PMID 35801486, 2022). "The IC50 value for CDK2 activity for PHA-767491 of 200 nM, compares with 600 and 500 nM for roscovitine and CVT-313, respectively, and PHA-767491 shows this effect on RB-positive cancer cells lines PC3, SW480 and SW620." (PMID 36009559, 2022). "Finally, the potent anti-cancer effects in the low micromolar range for PHA-767491 are mediated via potent DDK and CDK2 inhibitory activity that requires further investigation to determine its clinical significance in RB+ tumours." (PMID 36009559, 2022). "Cyclins and cyclin-dependent kinases (CDKs) are major effectors of the cell cycle with key role in cancer where our data shows downregulation of key cell-cycle proteins such as cyclin D1 and Geminin and mRNA levels of CCNE1, CCNF, CDK1, CDK2 and CDK5." (PMID 35902556, 2022). "These facts indicate that the combined treatment of a CDK6 degrader together with inhibitors of CDK2 and CDK4 may hold promising results and should be considered for future investigations, specifically for INK4low cancer cells." (PMID 35326705, 2022). "CDK2 and CDK1 are vital in tumors and therefore attractive targets for cancer therapy." (PMID 35115540, 2022). "Hence, our data provide evidence that expressions of CDK2/4/6 and STAT3 can be directly regulated by NSC765690 and NSC765599 with consequent antitumor implications in multiple cancer types." (PMID 33477856, 2021). "Therefore, a CDK2/4/6 triple-inhibitor appears to be a logical strategy for the treatment of HCC and many other cancers." (PMID 33579185, 2021). "Moreover, cyclization of the salicylanilide core scaffold of NSC765690 mediated its higher anti-cancer activities and had greater potential to interact with STAT3/CDK2/4/6 than did NSC765599 with an open-ring structure." (PMID 33477856, 2021). "Overall, our data disclose the novel molecular pathway METTL3/ADAR1/CDK2 connecting m6A and ADAR deaminases that can strongly change the scenario of post-transcriptional events with important consequences in cell homeostasis, differentiation, and cancer field." (PMID 33509238, 2021). "Due to the important roles of CDK2 in HCC, a CDK2/4/6 triple inhibitor may have additional advantages and broader anti-cancer activities than CDK4/6 dual inhibitors for the treatment of human HCC and other cancers." (PMID 33579185, 2021). "However, expressions of CDK2 and that of CDK4 correlated with CAF infiltrations in cohorts of 14 cancer types." (PMID 33668805, 2021). "We reasoned that since CDK2/4/6 and STAT3 clustering networks were enriched in cancer and inflammatory/immune-related pathways, then their hyper-expression levels in multiple cancers may be correlated with tumor immune infiltration." (PMID 33668805, 2021). "Recently, there have been studies on CDK4 and CDK6, but the mechanism of CDK2 in cancer is relatively lacking." (PMID 34409029, 2021).
cancer (continued). "Under normal conditions, the cell-cycle inhibitor p27 is localized in the nucleus where it binds to and inhibits Cyclin-dependent kinase 2 (CDK2); in many carcinomas including TC, p27 localization is mainly cytoplasmic, resulting in cell-cycle progression and tumorigenesis." (PMID 33578751, 2021). "Additionally, EV RNA sequencing revealed an enrichment of miRNAs, targeting different molecules linked to cancer progression (e.g., cyclin-dependent kinase (CDK) family: CDK2, CDK4, and CDK6) and cancer-survival signalling (PIK3R, RAS, MAPK, and STAT)." (PMID 32942702, 2020). "In accordance with these recent data, we found in this study that genetic depletion of Fasn resulted in the lower growth rate of c-Myc/MCL1/Cre tumors as well as in the decrease of Cdk1, Cdk2, Skp2, and Survivin/Birc5 genes, which have been previously found to be regulated by FASN in cancer cells." (PMID 33187130, 2020). "During the last two decades, CDK2 inhibitors have not been developed for contraception but instead predominantly to treat cancer." (PMID 32543655, 2020). "This shows that the effect of TNC on proliferation is cell type-specific and suggests that in cancer cells, the cdk2 complex is not repressed in the presence of TNC." (PMID 32817625, 2020). "The 3’UTR of several hallmark genes such as Cyclin-dependent kinase 2 (CDK2), Cyclin-dependent kinase 16 (CDK16), MAPK1 and NFKBIL1 are significantly longer in HPV positive cancer compared with HPV negative cancer." (PMID 31039132, 2019). "In HCT-15 cells, reduced transcription of cell cycle mediating genes (CCND1, PCNA, CDK2, CDKN1B), and reduced transcription of anti-apoptotic genes (BMI1, BIRC5 and BCL2), support a cancer suppressive and favorable FOXO3/FOXM1 ratio upon combined TNKSi/MEKi treatment." (PMID 30717152, 2019). "We first found that silencing of CCNE1 had minute impact on CDK2 level, in reminiscence of a recent report that overexpression and amplification of CCNE1 is dependent on CDK2 activity in Cyclin E1 driven cancer cell lines." (PMID 31313989, 2019). "CDK2 is mainly involved in the APC cell cycle regulation pathway, and the overexpression of CDK2 results in the upregulation of the G1/S phase transition, resulting in cancer cell proliferation." (PMID 31921802, 2019). "Several inhibitors of these proteins with different specificity have been developed as anti-cancer agents, including palbociclib (CDK4/6 inhibitor), flavopiridol, and dinaciclib (CDK9 inhibitors), milciclib (CDK2 inhibitor), SNS032 (CDK2/7/9 inhibitor), and THZ1 (CDK7 inhibitor)." (PMID 30841549, 2019). "CDK2 inhibition can also be highly effective in inducing apoptosis as it down-regulates the MCL-1 protein, leading to synergy with BH3 mimetics in various cancer cell line models." (PMID 30720718, 2019). "We found that according to the KEGG enrichment of the common DEGs deregulated upon SOX2OT inhibition; the pathways related to cancer (Kegg: 05200) is one of the most significant enriched pathway (p-value = 0.009285) with 6 genes (HIF1A, HRAS, CHUK, PIK3CA, CDK2, VHL)." (PMID 30202240, 2018). "The k-core factor was then applied to identify key regulatory genes, which likely play pivotal roles in gene interactions and regulation, including for key cancer genes, such as p21, FAS, CCND1, and CDK2; real-time PCR confirmed these genes after knockdown of HOXC-AS3." (PMID 30286788, 2018). "In addition, there is a significant increase in the activity of the CDK2, CCNE1 effector circuit as cancer stage progresses." (PMID 28042959, 2017). "Recently, CDK2, CCNE1 genes were described as cancer prognostic factors." (PMID 28042959, 2017).